PTPN22 (protein tyrosine phosphatase non-receptor type 22)
Diseases named in the same sentence as PTPN22 in open-access papers (continued):
Sharing a sentence is not in itself a finding about the gene and the disease.
Arthritis (14 papers, 2012 to 2025). Inflammation of a joint. "More importantly, the PTPN22-related alleles have a stronger interaction with arthritis-susceptible HLA-DR alleles." (PMID 32256192, 2020). "In this study, we showed that, whereas loss of PTPN22 improved the activity of mutant ZAP70skg/skg, this had little consequence for selection events in the thymus, and yet significantly reduced the development of arthritis following mannan injection." (PMID 27288531, 2016). "Contrary to expectation, Ptpn22 deficiency delayed the onset and severity of arthritis in SKG mice." (PMID 27288531, 2016). "Therefore, an in-depth functional study of PTPN22 gene polymorphisms in arthritis development may further improve our understanding of RA pathogenesis." (PMID 32256192, 2020). "In mouse models of experimental arthritis and DSS colitis, PTPN22 deficiency resulted in enhanced susceptibility and pronounced progression of disease, indicating that PTPN22 is required to protect from systemic and gastrointestinal inflammation." (PMID 32751912, 2020). "By performing functional assays with isolated neutrophils from PTPN22-deficient mice and by analyzing inflammation in K/B×N serum transfer arthritis, we demonstrate that PTPN22 regulates FcγR neutrophilic inflammation." (PMID 27807193, 2016). "Effect of the presence of the shared epitope and the minor rs7574865 allele in STAT4 or rs2476601 in PTPN22 on disease activity (DAS28) and disability (HAQ) in patients with early arthritis." (PMID 22937072, 2012). "In arthritis models, PTPN22 deficiency reduces disease severity in the arthritogenic serum-induced arthritis and autoimmune arthritis SKG mouse models, while it accelerates the development of arthritis in the KBxN mouse." (PMID 39944077, 2025). "PTPN22 encodes for a protein tyrosine phosphatase inhibiting signaling in T cells and it has been found to mediate, via Toll-like receptors, IFN-I response, suppressing arthritis and colitis in mice models." (PMID 38124740, 2023). "Arthritic joints from mannan-treated SKG and SKG Ptpn22−/− mice with comparable arthritis scores showed similar levels of cellular infiltrates (data not shown); however, loss of PTPN22 decreased both the likelihood of getting disease and the overall severity of the resulting arthritis." (PMID 27288531, 2016). "In our animal facilities, SKG mice up to the age of 6 mo did not develop any spontaneous arthritis or any systemic inflammation such as interstitial pneumonitis, as previously reported, and loss of PTPN22 did not make them any more susceptible to spontaneous disease up to ∼8 mo of age." (PMID 27288531, 2016). "Further studies have demonstrated that PTPN22 is capable of regulating the Th17 bias in mannan immunised SKG mice towards a Th1/Treg phenotype, protecting the mice from arthritis." (PMID 30054208, 2018). "On the contrary, we found that SKG mice lacking PTPN22 had both lower incidence and decreased severity of arthritis following induction of disease by administration of mannan." (PMID 27288531, 2016). "Given that the protection from K/B×N serum transfer arthritis afforded by Ptpn22−/− mice was larger than that of any individual SFK (Hck, Fgr, or Lyn), it is interesting to speculate that PTPN22 may contribute to regulating several SFKs, as well as other potential substrates." (PMID 27807193, 2016).
juvenile idiopathic arthritis (14 papers, 2012 to 2025). Juvenile idiopathic arthritis (JIA) is the term used to describe a group of inflammatory articular disorders of unknown cause that begin before the age of 16 and last over 6 weeks. "Juvenile idiopathic arthritis, the common type of autoimmune arthritis in children under 16, is also known to be associated with the PTPN22 1858T allele." (PMID 36013501, 2022). "The CT haplotype that includes the risk alleles from both PTPN22 polymorphisms (−1123G>C and +1858C>T) has shown a significant association with T1DM, RA, and juvenile idiopathic arthritis (JIA)." (PMID 28210620, 2017). "The PTPN22 gene, crucial in T-cell receptor signaling, is notably associated with increased risk for rheumatic diseases like RA, SLE, and juvenile idiopathic arthritis (JIA)." (PMID 38675400, 2024).
colitis (13 papers, 2013 to 2025). Inflammation of the colon. "Both loss of NLRP3 as well as PTPN22 resulted in aggravation of acute DSS colitis, while presence of the R619W variant protected the animals from developing intestinal inflammation." (PMID 32751912, 2020). "Mice expressing the murine R619W ortholog of the human R629W PTPN22 variant are protected in acute DSS colitis." (PMID 32751912, 2020). "In contrast, mice bearing PTPN22 with an autoimmunity-associated gain-of-function mutation causing increased phosphatase function are protected from DSS-colitis." (PMID 30455704, 2018). "In murine models, PTPN22 deficiency results in pronounced colitis, increased NLRP3 phosphorylation, but reduced levels of mature IL-1β." (PMID 28561062, 2017). "In our study, Ptpn22 demonstrated progressively increased expression within the colonic tissue of susceptible mice following the establishment of colitis." (PMID 23442222, 2013). "Phenotypic pathway analysis, text mining and time-course qPCR replication highlighted several potential cis-QTL candidate genes in colitis susceptibility, including FcgR1, Ptpn22, RORc, and Vav3." (PMID 23442222, 2013). "In a dextran sulfate sodium-induced colitis model, PTPN22 deficiency exacerbates colitis." (PMID 39944077, 2025). "Overall, our data show that presence of the IBD-associated variations within the PTPN2 and PTPN22 gene loci are related to significant alterations in intestinal microbiota composition what clearly resembles our previous findings in mouse colitis models using PTPN2 deficient mice." (PMID 29965986, 2018). "Using the T cell transfer colitis model, PTPN22 was shown to contribute to both effector and regulatory T cells in colitis." (PMID 30429852, 2018). "This activated phenotype persisted amongst PTPN22 KO T cells after restoration of homeostasis but did not lead to weight loss nor the induction of colitis." (PMID 32047502, 2020). "Finally, abnormalities of protein tyrosine phosphatase non-receptor 22 (PTPN22) activity were shown to be inversely associated with colitis." (PMID 33808793, 2021). "It follows from this that mice with PTPN22-deficiency manifest decreased NLRP3 inflammasome activity (and decreased IL-1β production) upon exposure to an inflammatory stimulus and therefore exhibit increased DSS-colitis in the same manner as do mice with frank NLRP3-deficiency." (PMID 30455704, 2018). "Murine colitis models indicate that PTPN22 does not solely play a role in the function of conventional T cells." (PMID 30429852, 2018).
Hashimoto thyroiditis (12 papers, 2009 to 2025). An autoimmune disorder caused by the production of autoantibodies against thyroid tissue. "Thus far, although some susceptibility loci have been elaborated, including PTPN22, FOXP3, and CD25, the aetiology and pathogenesis of Hashimoto’s thyroiditis remains unclear." (PMID 30384852, 2018). "Candidate gene studies have also suggested links between autoimmune hypothyroidism and PTPN22 (protein tyrosine phosphatase, non-receptor type 22 (lymphoid)), as well as the HLA (human leukocyte antigen) class II region, CTLA4 (cytotoxic T lymphocyte antigen 4), and 8q23-24." (PMID 22493691, 2012).
atherosclerosis (9 papers, 2008 to 2025). A disease characterized by the build-up of fatty material and calcium deposition in the arterial wall resulting in partial or complete occlusion of the arterial lumen. "Nevertheless, the molecular mechanism of how PTPN22 gene polymorphisms affect atherosclerosis remains unclear." (PMID 31191743, 2019). "Furthermore, genetic variants of PTPN22 increased the risk of atherosclerosis in people with autoinflammatory disorders." (PMID 31191743, 2019). "Recent reports have mentioned that PTPN22 ablation accelerates arterial thrombus formation and rat tail-bleeding time, suggesting that PTPN22 is a potential therapeutic target for cardiovascular diseases, atherosclerosis, and calcific aortic valve disease." (PMID 40305360, 2025). "Genetic polymorphisms of the protein tyrosine phosphatase non-receptor 22 (PTPN22) are reported to be involved in atherosclerosis and played a role in the immune response involved in the pathogenesis of CAD." (PMID 25123136, 2014).
multiple sclerosis (8 papers, 2012 to 2025). A progressive autoimmune disorder affecting the central nervous system resulting in demyelination. "Notably, the PTPN22 gene, which is associated with SLE and multiple sclerosis susceptibility, belongs to the same family of PTPN12." (PMID 35743441, 2022).
inflammatory bowel disease (7 papers, 2013 to 2024). A spectrum of small and large bowel inflammatory diseases of unknown etiology. "Here, we investigated associations of PTPN22 SNP rs2476601 in inflammatory bowel disease (IBD) patients in the Swiss IBD Cohort Study (SIBDCS)." (PMID 27467733, 2016). "In immune cells, differential gene expression analysis revealed that genes associated with immune regulation, biotic stimulus, and inflammatory bowel disease (IBD) were significantly upregulated, including Zfp36, Ptpn22, and Isg2017–19." (PMID 37488127, 2023). "Variations within the gene locus encoding protein tyrosine phosphatase non-receptor type 22 (PTPN22) are associated with the risk to develop inflammatory bowel disease (IBD)." (PMID 23991106, 2013).
psoriatic arthritis (7 papers, 2006 to 2023). Joint inflammation associated with psoriasis. "On the other hand, polymorphisms in IL23R, TNFAIP3, PTPN22 (tyrosine-protein phosphatase non-receptor type 22), IL12B, RUNX1 (CD8-lymphocyte activation and differentiation), IL13, KIR (killer-cell immunoglobulin-like receptor), and MAGI1 genes have shown association with psoriatic arthritis." (PMID 37628670, 2023).
thyroid disorder (7 papers, 2014 to 2025). "Consistently, we underlined that genetically determined expression of PTPN22 was positively associated in MR with the development of RA, thyroid disorder, and primary sclerosing cholangitis." (PMID 32358504, 2020). "Individuals with R620 polymorphism in the protein tyrosine phosphatase (PTPN22) gene encoding a T-cell protein are more likely to develop concurrent SLE and thyroid disease." (PMID 41234630, 2025). "In the present study, we found that III-3 carried the missense mutation of PTPN22 (A77G), but did not exhibit any thyroid disorder." (PMID 30384852, 2018). "Finally, we hypothesize that PTPN22 N26S may be similar to the R620W SNP as a risk locus, which can increase the risk of thyroid disease; however, it may not show disease in carriers." (PMID 30384852, 2018). "Similar to previous studies, we also observed pleiotropy for a number of loci in particular PTPN22 for JRA, T1DM, and Thyroiditis, IL5 for Eosinophilia, Asthma, and EoE and NDFIP1 for Mental Retardation traits and Cerebral Palsy." (PMID 25477900, 2014). "Genetically, HLA (HLADRB1) and non-HLA genes (JACK/STAT – PTPN22) seem to be involved in IBD and thyroiditis common pathways." (PMID 39968296, 2025).
endometriosis (6 papers, 2013 to 2024). The growth of functional endometrial tissue in anatomic sites outside the uterine body. "So far, no studies have been conducted to investigate the association between the mentioned polymorphism and URPL, but a statistically significant association has been found between the PTPN22 R620W polymorphism and endometriosis." (PMID 34805727, 2021). "A study on the Brazilian population in 2009 also showed that there was a statistically significant correlation between the presence of the PTPN22 620W polymorphism and endometriosis." (PMID 34805727, 2021). "For example, a study on the Italian population showed that the frequency of the PTPN22 620W allele in individuals suffering from endometriosis was higher than in healthy subjects." (PMID 34805727, 2021). "With a sample of over 1,624 for the PTPN22 (C1858T) polymorphism, our meta-analysis showed overall increased risk associations of up to 5.6-fold in endometriosis, significant in all genetic models." (PMID 28444099, 2017). "Additional well-designed studies, based on sample sizes commensurate with detection of small genotypic risks, should allow conclusions that are more definitive as to the association of PTPN22 (C1858T) polymorphism with endometriosis." (PMID 28444099, 2017). "However, few studies have been performed to investigate the association between the PTPN22 620W polymorphism and endometriosis, as one of the common complications of fertility." (PMID 34805727, 2021). "The associations observed between PTPN22 (C1858T) and the risk of endometriosis suggest that this polymorphism could be a useful marker of susceptibility to the disease." (PMID 32143537, 2020). "Nevertheless, the observed associations between PTPN22 and risk of endometriosis suggest this polymorphism might be a useful susceptibility marker for this disease." (PMID 28444099, 2017). "The associations observed between PTPN22 (C1858T) and the risk of endometriosis suggest this polymorphism might be a useful susceptibility marker for this disease." (PMID 28444099, 2017). "In the presence of endometriosis, the PTPN22 polymorphism may cooperate with clinical and genetic factors to influence the course of disease and immune reactions." (PMID 28444099, 2017). "These cooperative interactions could result in a statistical association between PTPN22 and endometriosis." (PMID 28444099, 2017). "Further investigations are needed to clarify the possible role of PTPN22 and other polymorphic systems in the clinical course of endometriosis." (PMID 28444099, 2017). "Endometriosis is present within families and is considered a heritable disease, as genes, including the protein tyrosine phosphatase non-receptor type 22 gene (PTPN22), the predisposing gene for human autoimmune diseases, are also associated with endometriosis." (PMID 39596309, 2024).
hypothyroidism (6 papers, 2012 to 2024). Abnormally low levels of thyroid hormone. "For instance, we observed a significant association of the gene variant rs2476601 (PTPN22) with hypothyroidism, T2D and hypoglycaemia." (PMID 39238070, 2024). "On chromosome 1, rs2476601, a previously known missense variant located on PTPN22, was genome-wide significant in both hyper- and hypothyroidism analyses (phyperthyroidism = 3.15 × 10−14; phypothyroidism = 3.49 × 10−124)." (PMID 30248900, 2018). "VAV3 is involved in immune function, and FOXE1 and PTPN22 have previously been associated with hypothyroidism." (PMID 22493691, 2012). "Among this list, only the CTLA4, PTPN22, and SH2B3 loci show significant association with hypothyroidism after correction for 107 multiple tests." (PMID 22493691, 2012). "Additionally, PTPN22, a gene of particular interest in our study, was found in both the T2D‐hypothyroidism/myxoedema and T2D‐hypoglycaemia trait pairs." (PMID 39238070, 2024). "The co‐localization of rs2476601 between T2D, hypothyroidism/myxoedema and hypoglycaemia, along with its high CADD score, implies a significant role in the development of these diseases, potentially through the functional regulation of PTPN22 gene expression." (PMID 39238070, 2024).
myasthenia gravis (6 papers, 2010 to 2025). Myasthenia gravis (MG) is a rare, clinically heterogeneous, autoimmune disorder of the neuromuscular junction characterized by fatigable weakness of voluntary muscles. "These included, for example, the non-synonymous PTPN22 SNP rs2476601 which was associated with myasthenia gravis (overall and the late-onset subset) by subset-selected FDR < 0.01." (PMID 33239102, 2020). "The distribution of the PTPN22 (rs2476601 T→C) genotype frequencies in healthy controls (HC) and myasthenia gravis (MG) patients." (PMID 25119822, 2014).
Obesity (6 papers, 2018 to 2025). Accumulation of substantial excess body fat. "PTPN22 is linked to obesity through its role in immune and inflammatory responses." (PMID 39594522, 2024). "The hub genes calculated by Cytoscape software are MNDA (score 320), CYBB (score 314), CD86 (score 312), FCGR2C (score 242), NCF2 (score 240), LCP2 (score 182), TLR8 (score 148), HLA-DRA (score 54), LCP1 (score 30), and PTPN22 (score 8), which are considered to be associated with obesity-related AF." (PMID 36671813, 2023). "Diverse genomic risk loci have been linked to diseases and traits, including PTPN22 for autoimmune disease and FTO (Fat mass and Obesity-associated) for obesity, according to a decade of GWAS." (PMID 39219434, 2025). "We also evaluated PTPN22 rs2476601 (G > A) and other clinical features in TS patients, such as obesity, as well as dyslipidemia, given its role in modulating inflammatory conditions." (PMID 30508004, 2018). "The positive correlation of genes such as HSD11B1, PTPN22, ABCC1, MMP9, FGF1, and F13A1 with M0 and M1 macrophages suggests a possible role in shaping the immune response toward a more beneficial phenotype in obesity." (PMID 39594522, 2024).
type-2 diabetes (6 papers, 2008 to 2024). "Studies assessing HLA, PTPN22 and INS in LADA, type 1 and type 2 diabetes." (PMID 36034444, 2022).
Addison’s disease (5 papers, 2012 to 2025). "Therefore, it is our opinion that the correlation between the polymorphism of PTPN22 gene and the occurrence of Addison’s disease in European population cannot be confirmed beyond a reasonable doubt as authors claim." (PMID 23072316, 2012).
alopecia areata (5 papers, 2012 to 2025). Loss of scalp and body hair involving microscopically inflammatory patchy areas. "The results suggest that the T allele of the single nucleoid polymorphism (SNP) rs2476601 in PTPN22 gene is a risk factor for developing alopecia areata." (PMID 34735462, 2021). "We have previously reported similarities in gene expression patterns and PTPN22 polymorphisms between alopecia areata (AA) patients and their healthy relatives, but not unrelated healthy controls." (PMID 37759685, 2023). "Association between genes PTPN22, FAS/FASL and CTLA4 with alopecia areata." (PMID 34735462, 2021).
Behcet disease (5 papers, 2012 to 2022). A chronic, relapsing, multisystemic vasculitis characterized by mucocutaneous lesions, as well as articular, vascular, ocular and central nervous system manifestations. "The present study was performed to assess the association between PTPN22 polymorphisms and Behcet's disease in two Chinese Han populations." (PMID 22396730, 2012). "Different studies have suggested that PTPN22 is a genetic risk factor for Behcet’s disease, a disorder that usually presents ocular damage as a major manifestation, although another study found that this gene does not seem to influence the ocular manifestation of this disease." (PMID 23559857, 2013). "In this regard, an implication of PTPN22/CSK in the susceptibility to giant cell arteritis, Behçet’s disease and ANCA-associated vasculitides has been described in Caucasians." (PMID 26458874, 2015). "Intriguingly, two studies reported that PTPN22 1858T can protect against Behçet’s disease (BD)." (PMID 36013501, 2022). "In line with that, although the genetic influence of PTPN22/CSK in several vasculitides (such as giant cell arteritis, Behçet’s disease and antineutrophil cytoplasmic antibody (ANCA)-associated vasculitides) has been demonstrated, there is scarce information on the role of PTPN22/CSK in HSP." (PMID 26458874, 2015).